ATR (ATR checkpoint kinase)
Diseases named in the same sentence as ATR in open-access papers (continued):
Sharing a sentence is not in itself a finding about the gene and the disease.
breast cancer (continued). "XRCC1 loss amplifies the sensitivity of pancreatic cancer cells to β-lapachone, triple negative breast cancers to the ATM, ATR, and Wee1 inhibitors, liver adenocarcinoma HepG2 to γ rays, and breast cancer cells to cisplatin, camptothecin, and MMS." (PMID 40271221, 2025). "First, GNPDA1 was strongly associated with “DNA damage_ATM activation by DNA damage (p = 4.282 × 10−06)”, “BRCA1 and BRCA2 in breast cancer (p = 6.950 × 10−04)”, and “DNA damage_ATM/ATR regulation of G2/M checkpoint: nuclear signaling (p = 8.093 × 10−04)”." (PMID 40278313, 2025). "In the current study we identify the role of the AEP/ATR/PPP1R10 axis in genotoxic stress tolerance in breast cancer patients." (PMID 40012043, 2025). "Among breast cancer subtypes, the top eight mutational rates were MAD2L2/FANCV (37.5%), FANCI (32%), ATR (32%), FAAP20 (30%), FAAP100 (28%), SLX4 (27%), FANCT (27%), and BRIP1 (26%) in breast invasive carcinoma NOS." (PMID 39421870, 2024). "It has been shown that CPX can induce DNA damage and activate the ATR-Chk1 pathway in breast cancer (MDA-MB-231) and rhabdomyosarcoma (Rh30) cells." (PMID 39513859, 2024). "Accordingly, combinatorial treatment with ATR inhibitors showed synergy with BUB1 inhibition in breast cancer cell lines with functional ATM activity." (PMID 38396175, 2024). "Another ongoing phase 1/2 trial also focuses on ATR inhibitors ART6043 monotherapy in advanced or metastatic HER2-negative BRCAm breast cancer (NCT05898399)." (PMID 39334297, 2024). "In BRCA2-mutant breast cancer, ATR inhibitors in combination with olaparib can also boost antigen presentation and inflammation in the TME by abrogating PDL1 upregulation and Treg cell recruitment." (PMID 38473997, 2024). "as a DNA repair inhibitor that interacts with Ku70/Ku80 and ATR at the protein level to impede breast cancer progression." (PMID 38098610, 2023). "Even less is known about the association of ATR/CHEK1 mutations, either germ line or somatic, with breast cancer incidence or outcome." (PMID 37390209, 2023). "Knockdown of RAD17 sensitizes breast cancer cells to cisplatin, which is consistent with our results of ATR inhibition reversing topotecan resistance." (PMID 35844787, 2022). "RNF126-expressing breast cancer cells exhibit CDK2-mediated replication stress that makes them potential targets for ATR inhibitors." (PMID 36539893, 2022). "Our results provide a proof-of-concept in preclinical models of a new paradigm for treating breast cancer with high expression of RNF126 via ATR inhibitors alone." (PMID 36539893, 2022). "In our model, we determined that breast cancer cells with a higher level of RNF126 are more sensitive to ATR inhibitors than breast cancer cells with a lower level of RNF126." (PMID 36539893, 2022). "In the initial step of this mechanism, unsynapsed chromosome axes (XY axes in MSCI) are recognized by BRCA1, the protein product of breast cancer susceptibility gene 113,40,41, by the ATR activator TOPBP122,24,42, and by ATR." (PMID 36443288, 2022). "ATR inhibitors were more effective at killing breast cancer cells with intact RNF126 due to replication stress compared with the corresponding cells with RNF126 knockdown." (PMID 36539893, 2022). "Treatment with ATR inhibitors increased cell death by triggering abnormal origin firing in breast cancer cells with higher RNF126 expression." (PMID 36539893, 2022).
breast cancer (continued). "Two ATR inhibitors were found to induce cytotoxicity and reduce the growth of murine and human breast cancer cell lines that were SLX4IPhigh/hTERTlow (ALT+)." (PMID 34069193, 2021). "More specifically, WEE1 and ATR inhibitors caused the synergistic killing of acute myeloid leukemia (AML), biliary tract, and breast cancer cells, likely due to problems arising in S-phase and G2/M." (PMID 34359691, 2021). "Germline and somatic BRCA1/2 and ATR were each significantly associated with higher SNV and indel neoantigen loads in breast cancer (FDR < 1.4 × 10−7)." (PMID 34095878, 2021). "The approach of simultaneous inhibition of WEE1 and ATR has emerged very recently and appears promising based on preclinical studies of breast cancer and AML." (PMID 34359691, 2021). "Deleterious germline variants in ATR and ATM were also associated with HRD phenotype in breast cancer, ATM in prostate, lung, and stomach cancers, and BRCA2 in stomach cancers." (PMID 34572800, 2021). "Patient survival was also highly correlated with the level of ATR in breast cancer cells (P = 0.0006)." (PMID 32414408, 2020). "In both cell types, absence or reduced ATR expression predicted poor clinical outcome in locally advanced breast cancers." (PMID 32414408, 2020). "The implication of cancer cells in ATR knockdown in CAFs has been proven in vitro by showing that breast cancer cells downregulate ATR in breast fibroblasts in an IL-6/STAT3-dependent manner and via AUF-1." (PMID 32414408, 2020). "We started the present study by assessing the ATR expression level in 10 paraffin-embedded sections from breast cancer tissues, including both tumor as well as their adjacent histologically normal tissues, by immunostaining using anti-ATR antibody." (PMID 32414408, 2020). "We have shown that the protein kinase ATR is downregulated in cancer cells and their neighboring CAFs in breast cancer tissues as compared to their respective adjacent normal tissues." (PMID 32414408, 2020). "We have used immunohistochemistry to assess the level of ATR in breast cancer tissues and their adjacent normal tissues." (PMID 32414408, 2020). "It was found that quercetin, catechin and fisetin intensified the sensitivity of breast cancer cells to cisplatin by inhibiting ATR-Chk1 pathway." (PMID 31936346, 2020). "This indicates that ATR is downregulated in cancer cells as well as in their neighboring CAFs in breast cancer tissues as compared to their respective adjacent normal tissues." (PMID 32414408, 2020). "The present findings show that ATR is downregulated in cancer cells and their neighboring CAFs in breast cancer tissues as compared to their respective adjacent normal tissues." (PMID 32414408, 2020). "APOBEC3B transcription is increased by an ATR/Chk1-dependent pathway in breast cancer, in addition to viral infection, PMA and interferon-α." (PMID 32880638, 2020). "In ER + breast cancer, similarly, MYC overexpressed tumours with high ATR levels are associated with worse survival (p < 0.001) including in patients who received endocrine therapy." (PMID 30746633, 2019). "Tumours with low ATM or high ATR levels in conjunction with MYC overexpression also have worse overall breast cancer-specific survival (BCSS) (p value < 0.05)." (PMID 30746633, 2019). "In breast cancer models, combination of ATR and WEE1 inhibitors inhibits tumor cells progression and metastasis process." (PMID 31412533, 2019). "Reported DSB repair variants in breast cancer comprise PALB2, NBN, RAD51, ATM, CHEK2, ATR, RAD50, and WRN." (PMID 31658756, 2019). "Similar mitotic defects were observed upon combined inhibition of PARP and ATR in Brca2−/− mammary tumor cells." (PMID 31529615, 2019). "Conversely, many genes frequently mutated in MPA/DMBA-induced tumors, such as ATR, FAT1, and KRAS, are rarely mutated in breast cancer." (PMID 31366361, 2019).
breast cancer (continued). "As expected, in contrast to ATR, we observed that low ATM was linked to aggressive phenotypes in MYC overexpressed breast cancers, including in ER+ tumours." (PMID 30746633, 2019). "A very recent study reported that treatment with ATR plus Wee1 inhibitors led to tumor remission and inhibited metastasis with minimal side effects in an orthotopic breast cancer model." (PMID 31362335, 2019). "In the current study, high ATR in MYC overexpressed tumours was linked to poor survival particularly in patients who received endocrine therapy providing further evidence for ATR as a predictive factor in MYC overexpressed ER+ breast cancers." (PMID 30746633, 2019). "Taken together, the clinical data suggest that nuclear PTEN deficiency as well as ATR and pChk1ser345 expression in nuclear PTEN-deficient breast cancers is associated with aggressive breast cancers." (PMID 29396668, 2018). "In the current study, we provide evidence that ATR and pChk1 expression in of PTEN-deficient breast cancer adversely impact on survival." (PMID 29396668, 2018). "This confirms that ATR is another important target of breast cancer cells in BSFs, and that this protein kinase plays key roles in the carcinoma-stroma cross-talk during breast carcinogenesis." (PMID 30410668, 2018). "The active status of ATR-deficient BSFs was next confirmed by showing that specific down-regulation of ATR enhances the EMT process in breast cancer cells in a paracrine manner." (PMID 30410668, 2018). "Together, these results indicate that ATR down-regulation in breast stromal fibroblasts triggers the EMT process in breast cancer cells in a paracrine manner, which demonstrates their active status." (PMID 30410668, 2018). "In summary our study provides a mechanistic rationale for the combination of IGF-1R or IGF pathway inhibitor with ATR inhibitors or other DNA damaging agents in breast cancer." (PMID 27472395, 2016). "The effects of suppressing ATR with siRNA were further tested in the ZR-75-1 ductal breast carcinoma cell line, which was previously shown to be resistant to IGF-1R inhibition (IC50 2μM for BMS-754807)." (PMID 27472395, 2016). "ATR was previously validated as a major determinant of PARP inhibitor sensitivity in breast cancer and ovarian cancer." (PMID 25965342, 2015). "Our study bolsters evidence for previously claimed ATM/ATR associations with breast cancer with observations of 4 ATM and 4 ATR truncations in breast cancer cases." (PMID 26689913, 2015). "Further, treatment with the hsp90 inhibitor AUY922 was also demonstrated to disrupt the chaperone association of hsp90 with ATR and CHK1, thereby depleting their expression levels in breast cancer cells." (PMID 25026298, 2014). "We therefore used a tagging SNP (tagSNP) approach based on recent SNP data available from the 1000 genomes projects, to investigate the roles of ATR and CHEK1 in breast cancer risk and survival." (PMID 23844225, 2013). "Here, we have carried out a more detailed study of the role of the ATR and CHEK1 in breast cancer risk and survival based on the more complete resources now available from the 1000 genomes project." (PMID 23844225, 2013). "To date, a small number of gene-based association studies have been carried out to investigate the roles of ATR and CHEK1 as breast cancer susceptibility genes, using a tagging SNP (tagSNPs) approach." (PMID 23844225, 2013). "Deregulation of the ATR signaling pathway has been related with various instances of breast cancer development." (PMID 22952604, 2012). "Previous studies in HR deficient ovarian and breast cancers that have acquired resistance to platinum chemotherapy and/or PARP inhibitor have implicated those genes enriched at collapsed replication forks during ATR inhibition." (PMID 40442403, 2025). "Notch1 has been shown to activate ChK1 through ATR in breast cancer, thus it is possible that its inhibition may result in reduced activation in melanoma cells." (PMID 40437523, 2025).
breast cancer (continued). "Notably, D43 demonstrates selectivity for both normal breast epithelial cells and breast cancer cells, suggesting its potential as an ATR expression inhibitor and DNA damage inducer in clinical applications." (PMID 38369538, 2024). "However, we have considered essentiality in a breast cancer specific manner and more importantly contextualised it alongside selectivity, as successfully demonstrated in the case of ATR inhibitors in previous studies." (PMID 38600325, 2024). "The most prevalent DEGs connected with WikiPathways route include retinoblastoma gene in cancer, G1 to S cell cycle control, cell cycle, DNA IR-damage and cellular response via ATR, miRNA regulation of DNA damage response, vitamin D receptor pathway, and integrated breast cancer pathway." (PMID 36723760, 2023). "NUSAP1 has been linked to chromosome instability and DNA damage response (DDR) pathways through upregulating BRCA1 expression and recruitment to DNA damage foci in breast cancer and through activation of Ataxia telangiectasia and Rad3-related protein (ATR) in glioblastoma." (PMID 37047232, 2023). "Additional agent RP-3500 targeting ATR in breast cancer is currently under clinical phase 1 trial." (PMID 36359297, 2022). "Furthermore, elevated ATR protein, phospho-ATR, and phospho-CHK1 expression are associated with a poor prognosis in bladder, ovarian, and breast cancers." (PMID 35684331, 2022). "We hypothesized that the lower efficiency of ATR inhibitors in breast cancer cells with RNF126 knockdown might be explained by the relative reduction in replication stress." (PMID 36539893, 2022). "Taken together, these data suggest a mechanism of action in which inhibition of ATR in intact RNF126 cells induces an increase in CDK2-mediated replication stress in breast cancer cells, ultimately leading to DNA damage, replication fork collapse, cell apoptosis, and cell death." (PMID 36539893, 2022). "In breast cancer cells, the combination of the ATR inhibitor VE-821 and PARP inhibitors synergize to promote cell death independent of HR-proficiency, and ATR inhibition via VE-821 overcomes PARP inhibitor resistance in BRCA-deficient cells by disrupting rewired HR and fork protection pathways." (PMID 35205643, 2022). "CDK2 may mediate the killing effect of ATR inhibitors on RNF126 high-expression breast cancer cells." (PMID 36539893, 2022). "Interestingly, our results showed that breast cancer cells with RNF126 knockdown were less sensitive to ATR inhibitors than the cells with intact RNF126." (PMID 36539893, 2022). "For instance, seven of the nine breast cancer-specific ATR residues are in the PRD." (PMID 33742106, 2021). "In contrast, ATR inhibition in breast cancer has been shown to be more cytotoxic to ALT+ cells." (PMID 34069193, 2021). "Therefore, we sought to investigate the possible implication of breast cancer cells in ATR downregulation in BSFs through IL-6 signaling." (PMID 32414408, 2020). "In family C, as the different cancer cases were deceased, we could only test a healthy brother of the index case who developed breast cancer for the VUS (p.Arg1436Gln in POLE and p.Pro2033Ser in ATR); the two of them carried both variants." (PMID 32522261, 2020). "In another cohort of 103 tumors from locally advanced breast cancer patients, we have shown that absence or reduced ATR expression in tumoral cells and their adjacent stromal fibroblasts is correlated with poor overall survival as well as disease-free survival." (PMID 32414408, 2020). "Therefore, we investigated here the role of the protein kinase ATR in breast stromal fibroblasts in the prognosis of locally advanced breast cancer patients." (PMID 32414408, 2020). "This indicates that breast cancer cells downregulate ATR in BSFs in an IL-6-dependent manner." (PMID 32414408, 2020).
breast cancer (continued). "Therefore, we tested the effect of breast cancer cells and IL-6 on the expression of ATR in BSFs, and have shown that breast cancer cells as well as pure recombinant IL-6 downregulate ATR in BSFs." (PMID 32414408, 2020). "Furthermore, ATR expression in CAFs was inversely correlated with tumor recurrence, progression, and patient survival, which was also highly correlated with the level of ATR in breast cancer cells." (PMID 32414408, 2020). "Whether ATM and ATR expressions influence clinical outcomes in MYC overexpressed breast cancers is unknown." (PMID 30746633, 2019). "In addition, the effect of cisplatin on ATR pathway activation was also distinct in luminal and basal-like breast cancer cells." (PMID 31189884, 2019). "We evaluated whether the level of the TLS DNA Pols and the ATR pathway correlate with the 3D culture-induced resistance to cisplatin also in a breast cancer basal-like cell line (MDA-MB-231 cells)." (PMID 31189884, 2019). "Although direct targeting MYC for cancer therapy has been challenging, the clinical data shown here would suggest that ATR-Chk1 pathway targeting could be an alternative anti-cancer approach in MYC-amplified breast cancers." (PMID 30746633, 2019). "Our results suggest that ATR blockage might be a latent strategy to enable the cisplatin use also for breast cancer patients." (PMID 31189884, 2019). "Finally, we also demonstrated that inhibition of ATR reverted several of the 3D microenvironment-mediated responses to cisplatin, increasing sensitivity of breast cancer cells to this classical anticancer drug." (PMID 31189884, 2019). "PTEN, ATR and pCHK1Ser345 protein level was evaluated in 1650 human breast cancers." (PMID 29396668, 2018). "We, therefore, investigated PTEN, ATR, and pChk1ser345 co-expression in clinical breast cancers." (PMID 29396668, 2018). "Furthermore, ATR up-regulation in active breast fibroblasts reduced their paracrine pro-migratory/-invasive effects on breast cancer cells." (PMID 30410668, 2018). "The data presented in this study provide a tantalizing possibility for a similar synthetic lethality targeting in BER-deficient ER+ breast cancers using inhibitors of DSB repair pathway such as those targeting ATM, ATR, and DNA-PKcs that are currently undergoing pharmaceutical drug development." (PMID 25111287, 2014). "Also, some meta-analysis studies found that SNPs in genes MDR, MTR, SLC4A7, ATR and CHEK1 were significantly associated with breast cancer susceptibility." (PMID 24386390, 2013). "No such mutation was found in either study, therefore ATR is unlikely to play a major role as a high penetrance gene in breast cancer predisposition." (PMID 17010193, 2006). "Although no truncating mutation was found in the ATR coding region of our French Canadian breast cancer cases, we identified 41 variants in ATR exonic and flanking intronic sequences." (PMID 17010193, 2006). "Thus, CDK2-mediated replication stress in breast cancer with a high level of RNF126 expression might be one of the reasons for the sensitivity of these breast cancer cells to ATR inhibitors." (PMID 36539893, 2022). "Thus, we hypothesized that breast cancer cells with RNF126 knockdown could be more sensitive to ATR inhibitors." (PMID 36539893, 2022). "Moreover, we also found that ATR's expression level cannot predict breast cancer cells' metastasis." (PMID 36539893, 2022). "In order to establish whether the prognostic power of the ATR expression level is independent of other well-known breast cancer risk factors, multivariate Cox regression analysis was conducted." (PMID 32414408, 2020). "Thus co-treatment with ATR inhibitors might be a promising strategy for enhancement of cisplatin treatment efficiency in breast cancer patients." (PMID 31189884, 2019).